MTOR (mechanistic target of rapamycin kinase)
Diseases named in the same sentence as MTOR in open-access papers (continued):
Sharing a sentence is not in itself a finding about the gene and the disease.
tumor (continued). "In this regard, it has to be highlighted that switching off the PI3K/AKT/mTOR, MAPK/ERK, or Wnt/β-catenin signaling pathways can revert EMT to MET and halt tumor cell invasion." (PMID 34948338, 2021). "FBXW7 is a well-acknowledged tumor suppressor that promotes the degradation of multiple oncogenic proteins such as cyclin E, MCL1, c-Myc, mTOR, and Rictor." (PMID 33670113, 2021). "This revealed significant downregulation of mTOR pathway activity in both HER2/neu and Wnt1 residual tumor cells compared to their corresponding primary or recurrent tumor cells." (PMID 34088357, 2021). "BBR-mediated apoptosis blocks the AMPK/mTOR/ULK1 pathway and decreases tumor growth in glioblastoma polymorphic (GBM) cells in vivo." (PMID 34885950, 2021). "Intriguingly, mTOR composes networks of crosstalk with the signaling pathways within the PI3K/AKT pathway and the inhibition of mTOR determines the minimization of MVD and suppresses the tumor growth." (PMID 34940041, 2021). "Suppressor of cytokine signaling‐5 (SOCS5), a member of the SOCS protein family, has also been found to promote tumor cell invasion and metastasis in hepatocellular tumors by up‐regulating PI3K/Akt/mTOR‐mediated autophagy pathway." (PMID 34977870, 2021). "Altogether, these data indicate that the alpelisib and palbociclib combination induces tumor regression in c-Met/H1047R mice by suppressing MAPK, AKT/mTOR, and cell proliferation pathways." (PMID 34625531, 2021). "WEE1 and mTOR inhibitor induced efficient apoptosis in KRAS-mutant NSCLC cell lines and suppressed tumor growth in mice model." (PMID 34301278, 2021). "In summary, these data indicate that the combination of alpelisib and MLN0128 induces tumor regression in the c-Met/H1047R mouse HCC model via suppressing MAPK, AKT/mTOR, and cell proliferation pathways." (PMID 34625531, 2021). "The mammalian target of rapamycin (mTOR) and the PI3K/mTOR/Akt signaling pathway play a role in tumor proliferation, survival and angiogenesis." (PMID 34065268, 2021). "In CRC, miR‐802 reduces the activation of the PI3K/AKT/mTOR pathway by down‐regulating RAN, thereby inhibiting tumor cell proliferation, metastasis, and invasion." (PMID 34558723, 2021). "In summary, the data suggested BI853520 suppressed primary tumor proliferation both in vitro and in vivo through PI3K/AKT/mTOR signaling pathway." (PMID 35201437, 2021). "Recent preclinical studies have shown that DPP-4i can increase viability and proliferation of tumor cells, and accelerates EMT through the CXCL12/CXCR4/mTOR axis both in vitro and in vivo." (PMID 36860286, 2021). "A recent study confirmed our results and suggested that inhibition of GSK3β decreased p-mTOR levels and downstream molecules, which were related to cell survival and growth in HCC cells and inhibited tumour growth in vivo." (PMID 34380537, 2021). "To explore the role of the mTOR pathway in MEC CSC, we performed Western blots from bulk MEC tumor cells treated for 24 h with increasing concentrations of several inhibitors of the mTOR pathway." (PMID 33479203, 2021). "Downregulated PI3K/AKT/mTOR pathway and its subsequent downstream p70S6K and E4-BP1 proteins.Inhibited tumor growth and induced apoptosis." (PMID 34026649, 2021). "On the other hand, the anti-tumor effect of PI3K, Akt, and mTOR inhibitors can directly present as the inhibition of tumor cell proliferation and angiogenesis, as well as the survival enhancement of CD8+ T cells." (PMID 34177907, 2021). "mTOR inhibitors have been extensively evaluated in HNSCC and despite an improved early outcome, the development of drug-recalcitrant tumor cells leads to recurrence." (PMID 35048066, 2021). "PI3Kγ is involved in Akt/mTOR signaling, inhibition of NF-κB activation, and in the regulation of tumor immune inhibition by promoting MDSC migration to the tumor environment as well as by stimulating the immunosuppressive transformation of MDSCs." (PMID 33619235, 2021).
tumor (continued). "mTOR is a downstream molecule of AKT1, and the AKT/mTOR pathway is one of the classical signaling pathways mediating tumor metabolic homeostasis." (PMID 33718157, 2021). "Here we used CK-3, a dual blocker of the PI3K/AKT/mTOR and MAPK/ERK pathways, against HCC cell lines to verify its anti-tumor activity in vitro." (PMID 34395292, 2021). "In conclusion, the Akt/mTOR and ERK pathways play a fundamental role in cancer, and drugs targeting these pathways are expected to provide new options for tumor treatment." (PMID 34988073, 2021). "The hyperactivation of the mTOR pathway and oncogenes such as MYC, RAS and AKT are key determinants for the activation of the DNSP, which contributes to the proliferation of tumor cells." (PMID 34066940, 2021). "It investigated a novel preclinical PI3K/mTOR/PIM inhibitor (IBL-301) in vitro and in patient-derived NSCLC tumor tissues." (PMID 33946744, 2021). "While these pathways are well known to drive tumor cell proliferation and survival, they also promote metabolic alterations via activation of the PI3K/AKT/mTOR pathway that result in increased aerobic glycolysis." (PMID 34731180, 2021). "Treating with Topo I inhibitor Irinotecan and mTOR inhibitor AZD2014, acted synergistically to induce apoptosis and block protein synthesis resulting in tumor cell death." (PMID 33987182, 2021). "The PI3K/AKT/mTOR and MAPK/ERK signaling pathways play a crucial role in HCC tumor formation, cell cycle, apoptosis and survival." (PMID 34395292, 2021). "For these studies, we chose PI3K/mTOR and MEK pathway inhibitors because responses in different pHGG lines varied and target engagement can be reliably detected in tumor tissue." (PMID 34215733, 2021). "Having defined the mTOR and Hippo/YAP pathways as critical to TNBC tumor development, we next explored the therapeutic value of our findings." (PMID 34031411, 2021). "In CRC, upregulation of lipid metabolic enzymes such as FASN and ACC leads to tumor progression and metastasis through activation of oncogenic pathways including Wnt, PI3K/AKT, AMPK/mTOR." (PMID 34200820, 2021). "Western blot analysis was used to investigate the effects of taxifolin on mTOR and PI3K pathway activities in tumor cells." (PMID 34462635, 2021). "We found that PKI-587, combined with radiation, enhanced the anti-tumor and radiosensitizing effects by inhibiting the PI3K/AKT/mTOR and DNA damage repair pathways." (PMID 34665844, 2021). "Because the PI3K/AKT/mTOR signaling pathway is hyper-activated by the deletion of PTEN, which acts as a tumor suppressor to regulate cell proliferation and cell death, resistance to EGFR-TK inhibitor is increased in MBA-MD-468 cells." (PMID 34681198, 2021). "Some important classical pathways related to tumor development, such as the Hippo pathway, TGF-beta pathway, Ras signaling pathway, mTOR pathway, PI3K-AKT pathway, Wnt pathway, and AMPK pathway, were involved." (PMID 33690171, 2021). "By contrast, the failure of tumor suppression by BO under pseudo germ-free (PGF) condition came with indistinctive changes in autophagy and mTOR activity, implying the critical role of the gut microbiota in BO’s anticancer activity." (PMID 34658867, 2021). "Under W922 treatment, the suppression of tumor growth was observed, as well as dephosphorylation of PI3K/AKT/mTOR proteins and mTOR inhibition." (PMID 34638601, 2021). "We also observed that in tumor lysates from the treated mice that the NR4A1-regulated gene products EGFR, cMET, PD-L1, and phosphorylated mTOR were decreased and that these in vivo results complement the in vitro studies in MDA-MB-231 cells." (PMID 34072371, 2021). "The mTOR signaling pathway regulated by AMPK and LAT1 functions as a sensor of dynamic alterations in the nutrient tumor microenvironment." (PMID 33401672, 2021).
tumor (continued). "Upregulated AXL and its interaction with EGFR were associated with resistance to PI3Kα inhibition due to sustained mTOR activation, and addition of AXL inhibitor R428 sensitized tumor cells to PI3Kα." (PMID 34830794, 2021). "We investigated the efficacy and effect on cell signaling of novel preclinical PI3K/mTOR/PIM kinase inhibitor (IBL-301) in NSCLC cell lines and patient tumor tissue explants." (PMID 33946744, 2021). "Abnormal activation of signal transduction pathways related to tumor cell metabolism plays an important role in tumorigenesis and development, such as PI3K/AKT/mTOR signaling pathway." (PMID 33343350, 2020). "PI3K/Akt/mTOR (mammalian target of rapamycin) signaling pathway is involved in the constitutive activation of BCR signaling and cell adhesion-mediated drug resistance within tumor microenvironment." (PMID 33317571, 2020). "Taken together, our results demonstrate that simultaneous blockade of JAK/STAT3, PI3K/AKT/mTOR, SRC and MEK/MAPK pathways results in better anti-tumor activity compared to inhibiting any one or two or three of these signaling pathways." (PMID 32927828, 2020). "Recently, mTOR-generated signal was suggested to play a positive role in the IFN-related biological roles, including T cells immune response and tumor regression." (PMID 32483450, 2020). "As an important tumor suppressor, FBXW7 participates in the degradation of many oncogenes, such as Myc, c-Jun, cyclin E, mTOR, Notch-1 and Mcl-1." (PMID 32296023, 2020). "Besides, new methods such as GWAS, which located a new gene NR2F2 involved in LAM, and systems biology approach, which found the correlation of mTOR with DNA damage checkpoint, used in tumor research could help open minds in studying new targets, which, however, need to be further validated." (PMID 33072782, 2020). "During tumor progression, tumor metabolism is regulated by a number of metabolic regulators, including HIF-1α, AMPK, mTOR, and PPAR gamma coactivator 1 alpha (PGC-1α), wherein AMPK indirectly regulates the stability of HIF-1α through metabolites." (PMID 33109235, 2020). "In conclusion, this study provides the first demonstration that GA exerts the anti-tumor effects through inducing apoptosis and inhibiting PI3K/AKT/mTOR pathway." (PMID 32913452, 2020). "This approach allowed for the detailed investigation of the interplay between Akt/mTOR and HIF signaling during tumor reoxygenation after radiotherapy." (PMID 32545356, 2020). "To further study the functional relationship of mTOR and TF in these tumors, we investigated the effects of an anti-TF antibody SC1 on tumor microenvironment." (PMID 32923403, 2020). "To elucidate the mechanism mediating these tumor-suppressive effects of exercise, we examined the AMP-activated protein kinase (AMPK)—mTOR signaling pathway in liver homogenate." (PMID 32486073, 2020). "Prevents cell tumor through autophagy (by AMPK activation and inhibition of mTOR, major inhibitor of autophagic flux); able to block the autophagosome fusion with lysosomes." (PMID 33143272, 2020). "Specifically, the tumor-inhibitory effects of rutin have been shown to be exerted through the regulation of various signaling pathways, such as PI3K/Akt/mTOR, NF-κB, Nrf2, ERK, p38 MAPK, and JNK." (PMID 32823876, 2020). "In order to analyse the possibility that the failure of AKT/mTOR inhibition on xenotransplanted MPNST cells in vivo is due to restoration of AKT and mTOR signaling, we performed western blot analysis of the tumours." (PMID 32102484, 2020). "PTEN deletion is frequently detected in 5% of HCCs, while over-expression results in the tumor size reduction and further activation of the PI3K-Akt-mTOR pathway." (PMID 33260729, 2020).
tumor (continued). "As a widely studied tumor suppressor gene, PTEN has the ability to suppress signal transduction of the Akt/mTOR pathway." (PMID 31899608, 2020). "Neurofibromin is a tumor suppressor that regulates RAS signaling in the cytoplasm, and hence also its downstream mediators, PI3K (phosphatidylinositol 3-kinase)/mTOR (mammalian target of rapamycin)." (PMID 32630739, 2020). "The same group further characterized this direct effect in a panel of different tumor and endothelial cells using dactolisib and another dual PI3K/mTOR inhibitor, NVP-BGT226." (PMID 32903756, 2020). "Celecoxib or metformin in combination with other drugs reduces the phosphorylation level of mTOR by inactivating the PI3K/Akt/mTOR or AMPK/mTOR signaling pathways, resulting in tumor inhibition 59-61." (PMID 33033527, 2020). "As our expectation, the protein expressions of Jagged2, Notch, MMP-2/MMP-9 and PI3K/AKT/mTOR signaling were significantly reduced by Mel treatment and further significantly reduced by silenced Notch/JAG2 in the harvested tumor mass." (PMID 32792862, 2020). "Congruent to its tumor suppressor function and as a negative regulator of the PI3K/AKT/mTOR pathway, the downregulation/inactivation of PTEN results in an activation of this pathway and thereby supports cell growth and survival." (PMID 31936793, 2020). "Mechanistic studies identified that ART led to tumor cell apoptosis and cell cycle arrest by downregulating the ER-α expression and activating the LKB1/AMPK/mTOR pathway." (PMID 33511117, 2020). "PTEN is a tumor suppressor gene that dephosphorylates PIP3 and blocks Akt activation and serves as a negative regulator of PI3K/AKT/mTOR signaling pathway." (PMID 32093152, 2020). "Tumor samples from the MSI-N1014 group showed markedly reduced expressions of LGR5, β-catenin, IL-6, and mTOR, but increased expression of the tumor suppressor, miR-142-3p, according to qRT-PCR analysis." (PMID 32560222, 2020). "Currently, CKD4/6 inhibitors, mTOR (mammalian target of rapamycin) inhibitors and PI3K (phosphatidylinositol-3 kinase) inhibitors are investigated in order to overcome tumor resistance occurred through genetic and molecular changes." (PMID 33552000, 2020). "Knockdown of TTK protein inhibits the activation of Akt‐mTOR signaling pathway and reveals the mechanism of TTK involvement in tumor formation." (PMID 32530571, 2020). "PTEN (phosphatase and tensin homolog on chromosome 10) is a tumor suppressor, which dephosphorylates PIP3, thereby inhibiting the AKT/mTOR pathway." (PMID 32190669, 2020). "The anti-tumor effects of resveratrol, curcumin and paclitaxel have been reported based upon the inhibition of the TGF/SMAD, NFκ-B, PI3K/Akt/mTOR, NOTCH and JAK-STAT pathways." (PMID 33292283, 2020). "In mice, PD-1 blockade reverses glucose restriction in TILs, enhancing CD8+ T cells glucose influx and glycolysis via mTOR signaling, which allows IFN-γ production, improving their effector anti-tumor function." (PMID 32642279, 2020). "Taken together, these data demonstrated that cir-ITCH plays a tumor-suppressive role in human PCa cells, partly through the Wnt/β-catenin and PI3K/AKT/mTOR pathways." (PMID 32904490, 2020). "The results showed that alkaline microenvironment inhibited the viability and invasion of GC cells and the expression of mTOR, AKT, Wnt, Glut, and HIF-1α genes and proteins, promoted tumor cell apoptosis, and inhibited GC progression." (PMID 32211041, 2020). "IHC analysis and western blot analyses revealed that the levels of p-mTOR, p-p70S6K, and p-RPS6 in tumor tissues were inhibited by DHA in vivo." (PMID 33658929, 2020). "The activated AKT phosphorylates various protein kinases and mediates transcription factors, the mammalian target of rapamycin (mTOR), an important downstream in PI3K and AKT signal pathway, can regulate tumor cell proliferation and metastasis." (PMID 33117085, 2020).
tumor (continued). "We further showed that ZJQ-24 reduces the tumor growth in a HepG2 xenograft model through suppression of VEGF and AKT/mTOR pathways." (PMID 33116125, 2020). "GAB2 performs all these various oncogenic functions by mediating PI3K/AKT1/mTOR, MAPK, and IKKβ pathways in tumor cells that harbor GAB2 alteration." (PMID 33488950, 2020). "Results showed association of these miRNAs with signaling cascades closely related to tumor growth, including MAPK, adherens junction, mechanistic target of rapamycin (mTOR), and PI3K-AKT pathways." (PMID 32412911, 2020). "In the last years, several molecular targets have emerged and new drugs, targeting PI3K/Akt/mTOR and cyclinD/CDK/pRb pathways and tumor microenvironment have been integrated into clinical practice." (PMID 33105796, 2020). "Emerging evidence demonstrates that the AMPK/mTOR/ULK1 signaling pathway is a critical regulator of tumor autophagy, and participates in the progressions of numerous tumor types." (PMID 33292257, 2020). "Lack of miR-17 and miR-20a was shown to reduce glycolytic and oxidative metabolism in tumour cells and increase AMPK and decrease mTOR signalling pathways." (PMID 33379359, 2020). "LINC01419 silencing inhibits the activation of the PI3K/AKT1/mTOR pathway, as demonstrated by reduced phosphorylation of AKT1 and mTOR, thus promoting autophagy of GC cells as well as inhibiting tumor growth and metastasis." (PMID 32754285, 2020). "The miR-199 family has emerged as tumor suppressors in HCC by targeting critical genes of MET, transmembrane glycoprotein, and mammalian target of rapamycin (mTOR) pathways." (PMID 32964027, 2020). "Although their genetic basis and phenotype are different, they are both tumor-prone disorders resulting from the dysregulation of components of the convergent RAS/MAPK and PI3K/AKT/mTOR pathways." (PMID 32894194, 2020). "Immunohistochemistry further confirmed ZJQ-24 inhibited the tumor growth through suppression of VEGF and AKT/mTOR pathways in vivo." (PMID 33116125, 2020). "Several research groups have shown that high-level mTOR expression is needed to control apoptosis by BCL-2 family members, thus promoting tumor cell survival." (PMID 32131492, 2020). "In tumor cells, the classical PI3K/AKT/mTOR signaling pathway is often highly expressed and is involved in regulating cancer growth, proliferation, invasion, and metastasis." (PMID 32547948, 2020). "GO and KEGG analyses of these SMG5-related PCGs revealed them to be primarily enriched in the mTOR, AMPK, VEGF, and hepatitis B signaling pathways, indicating that they are closely related to tumor development." (PMID 33228611, 2020). "Many studies showed that activating mTOR signaling would promote a variety of pro-angiogenesis-related protein expressions, including HIF1α, VEGF, PDGF, FGF, and TGFβ in various types of tumor tissues." (PMID 32908897, 2020). "Tumour cells of the control group exhibited diffuse and strong expression of p‐cKIT, p‐AKT and p‐mTOR; a high Ki‐67 proliferative index; and few TUNEL‐positive apoptotic cells." (PMID 31957165, 2020). "In our study, the activated form of mTOR protein is upregulated in metastases and downregulated in HCC, suggesting its prominent role as an anabolic protein, which promotes tumor growth and proliferative processes." (PMID 33362215, 2020). "The mTOR cascade also shows ability to shape different paracrine and autocrine stimuli in TME and modulates tumor immunity." (PMID 32483450, 2020). "Reductions in PI3K/mTOR and ERK pathway activity were seen in the serial tumor biopsies done, which were only successfully performed in one patient (MCL with PR)." (PMID 32033478, 2020).